TNF (tumor necrosis factor)
Diseases named in the same sentence as TNF in open-access papers (continued):
Sharing a sentence is not in itself a finding about the gene and the disease.
tumor (continued). "Activated CD56+ILC3s from donor and patient LN could acquire cytotoxic capacity producing IFN-γ or could promote a pro-tumor immune response inducing the production of tumor necrosis factor α (TNF-α)." (PMID 36341381, 2022). "Tocilizumab, an IL-6R antibody, could induce the production of tumor immunity-stimulating factors, such as IL-12, IL-1β, and anti-tumor cytokines, such as TNF-α, and IFN-γ." (PMID 35681617, 2022). "Studies have proved that eIF4A3 regulates tumor cell function and drug resistance by regulating the TNF-α/NF-kB signaling pathway, whether this signaling pathway was involved ineIF4A3-regulated GC carcinogenesis needs further investigation." (PMID 35873631, 2022). "In addition, TNF-α and IL-6 have been found to promote tumor cell proliferation, invasion, metastasis and angiogenesis in cancers." (PMID 36335201, 2022). "(1975) showed that TNF-α was capable of inducing tumour necrosis." (PMID 36059680, 2022). "We achieved optogenetic control production of immunomodulatory cytokines (IFN-β, TNF-α and IL-12), which conferred strong protection against post resection tumor recurrence and improved long-term survival rates compared with the cytokine loaded implant systems." (PMID 36289204, 2022). "In addition, TNF-alpha, IL-17, and IL-6 have also been shown to induce tumor growth through NF-kappa B and STAT3 activation." (PMID 35563010, 2022). "IL6/JAK/STAT3 signaling and TNFα signaling via NFκB were positively enriched in the active clusters, suggesting that cytokine signaling, likely from the microenvironment, triggers tumor cell awakening." (PMID 36008376, 2022). "Moreover, TRAF2 and the cIAPs have recently been identified as major targets facilitating CD8+ T-cell elimination of tumor cells in a TNF-dependent manner in vivo." (PMID 36339601, 2022). "TNF can kill some tumor cells in vivo and in vitro or inhibit proliferation." (PMID 36035842, 2022). "Further, TNFα-treatment in BCSCs induced a pre-metastatic niche through breast-liver organ crosstalk by inducing vascular cell adhesion molecule-1 (VCAM-1) enriched neovasculogenesis in the liver of tumor-bearing mice." (PMID 36290384, 2022). "TNF-α is widely recognized as among the main mediators of cancer-related inflammation, mediating all steps of tumorigenesis, such as proliferation, invasion, angiogenesis, and metastasis formation, by accelerating tumor invasion and metastasis through EMT." (PMID 35454852, 2022). "Under conditions of chronic inflammation, IFN-γ secretion by Th1 lymphocytes seems to play a pivotal role in preventing tumor cell proliferation, while IL-13 derived from Th2 lymphocytes and TNF-α, IL-6, and IL-17 produced by Th17 cells promote dysplastic cell proliferation and tumor growth." (PMID 35264972, 2022). "Therefore, after combined immunotherapy, inflammatory immunosuppressive tumor microenvironment was remodeled, the secretion of TNF-α should be reduced." (PMID 34875483, 2022). "More importantly, increased TNF-α production may also release many important chemokines that significantly contribute to tumor angiogenesis, either directly or indirectly." (PMID 35955463, 2022). "However, studies on non-CAR T cells show that the TME impairs T-cell extravasation through irregular vasculature caused by tumor-induced angiogenesis and by downregulating extravasation mediators (including L-selectins, LFA-1, Mac-1, ICAM-1, and TNF-α)." (PMID 36429054, 2022). "Moreover, immune signaling pathways, including TNF signaling pathway, chemokine ligand 12 signaling pathway, and cytokine production, act a critical role in tumor." (PMID 36275743, 2022). "The production of TNF-α by inflammatory cells can facilitate the survival of tumor cells." (PMID 35910198, 2022). "TNFα is known to have dual effects on the tumor microenvironment." (PMID 36366531, 2022).
tumor (continued). "Although closely linked to the expression of TNF in the tumor context, these data suggest a role of SPATA2 in tumorigenesis which will necessarily have to be confirmed by further investigations into other neoplasms." (PMID 36402749, 2022). "Furthermore, the results showed that the level of TNF-α was high in BCP with progressed tumour phenotypes in comparison with those with less progressed tumour phenotypes." (PMID 35928364, 2022). "Although TNF can kill tumor cells, it also contribute to tumorigenesis." (PMID 35754839, 2022). "Numerous studies have indicated leptin, IL-6, and TNF-α could enhance the metastatic properties of tumor cells by activating of NF-KB or STAT3 signal pathway." (PMID 36361525, 2022). "Interestingly, in the context of this review, in animal models, TNF was essential for suppressing the number of M2 tumor macrophages and improved the chances of a positive outcome." (PMID 36358688, 2022). "TNF-α plays an important role in tumor promotion and progression." (PMID 35432485, 2022). "M1-macrophages prompted the destruction of tumor cells, recruited tumor-killing leukocytes, and engulfed tumor cells by producing the immune-killing molecules such as ROS and nitrogen and inflammatory cytokines such as IL-6 and TNF-α." (PMID 35585567, 2022). "Several stimuli, such as microbial pathogens, carcinogens, endotoxins, free radicals, interleukin 1 (IL-1), interleukin 6 (IL-6), lipopolysaccharide (LPS), tumor-necrosis factor (TNF), tumor promoter, and radiation (UV-light, X-rays, γ-rays), trigger the activation of NF-κB." (PMID 35408483, 2022). "Moreover, G6 treatment also induced the most secretions of cytokines in the tumor, wherein the high expressions of IL‐6 and TNF‐α in the tumor benefited CAR‐T immunotherapy against solid tumors through expanding CTLs and CAR‐T cells." (PMID 36156442, 2022). "IL-1, IL-6, IL-11, IL-15, IL-17, IL-23, and TNF-α are representative proinflammatory cytokines promoting tumor cell differentiation, proliferation, and survival that build up the tumor microenvironment and tumor inflammation." (PMID 36438839, 2022). "The combination therapy could elevate IFN-γ and TNF-α and decrease IL-17A in the serum of the tumor-bearing mice, which may contribute to the increase of TILs and the antitumor immunity." (PMID 35873573, 2022). "It is worthy to note that putrescine exerts anti-inflammatory function by inhibiting IL-8 and TNF-α in a LPS-stimulated inflammation model, which may provide a survival mechanism for tumor cells to evade immune response." (PMID 36119047, 2022). "Tumor cell kill was associated with cytokine, granzyme B (GZMB), and perforin production, with higher maximum levels after prolonged incubation, except for TNFα, which showed the highest levels after 24 h." (PMID 36271507, 2022). "Moreover, an increased level of interleukin (IL)-2, 6, 12, interferon-γ (IFN-γ), and tumor necrosis factor-α (TNF-α) in the spleen lymphocytes of CV-treated tumor-bearing mice reflected immunomodulation properties of CV aqueous extract." (PMID 35807802, 2022). "In mouse models, STING agonists synergise with radiotherapy to control local and distant disease and mediate rejection of tumour rechallenge via early T-cell-independent and TNF-α-dependent haemorrhagic necrosis, followed by a later stage of CD8 T-cell-dependent control." (PMID 36106115, 2022). "Moreover, combinational treatment with TNF-α showed synergistic anti-tumor effects in pancreatic cancer cells." (PMID 36361505, 2022). "The tumor antigens (including polypeptide, RNA, DNA, and tumor lysates) are loaded into the immature DCs, which are then presented on MHCs, and the various cytokines (for example, of GM-CSF, of IL-.4, of TNF-α, and IL-6 under) action to maturity." (PMID 35045874, 2022).
tumor (continued). "Genistein suppresses TNF-α-induced NF-κB activation as well as nuclear factor of kappa light polypeptide gene enhancer in B-cells inhibitor (IκB) kinase and IκB phosphorylation resulting in an inhibition of inflammation in the tumor microenvironment." (PMID 36307808, 2022). "On the other hand, tumor growth and progression are strictly connected to TNF signaling." (PMID 36497228, 2022). "The results of this study showed that the level of serum inflammatory factors (TNF-α) in the breast group patients was significantly higher than that in the benign breast group and the healthy group, and with the aggravation of the disease, the serum TNF-α level gradually increased." (PMID 35783155, 2022). "ELISA detection of inflammation-related factors (INF-γ and TNF-α) further showed that tumor tissues from mice treated with LV-LINC00665 and irradiation presented with decreased levels of INF-γ and TNF-α, which could be reversed additional sh-AhR treatment." (PMID 35918714, 2022). "In MC38-transplanted tumor tissue, TMP195 not only increased the proportion of M1 macrophages but also promoted the expression of M1 macrophage-associated inflammatory cytokines, including IL-12, TNFα and inducible nitric oxide synthase (iNOS)." (PMID 36263186, 2022). "We first investigated whether TPA particles encoding native or secreted versions of TNFα could potentially be effective to deliver TNFα to tumours." (PMID 35758207, 2022). "Furthermore, C3a and C5a are efficient stimulators of inflammatory mediators like IL-1β, IL-6 and TNF-α, and inflammatory processes are vital for tumor development, promoting subthreshold neoplastic tumor states to fully cancerous states." (PMID 36547187, 2022). "Immunofluorescence and immunohistochemistry results revealed that the V-L-R-H could efficiently decrease the TNFα concentration in the tumor microenvironment." (PMID 35933373, 2022). "It has been widely described how inflammatory cytokines, such as TNF-α, IL-1, and IL-6, can be produced by tumor cells, fact which may explain the link between cancer and inflammation." (PMID 35457471, 2022). "Moreover, the production levels of TNF-α, an important cytokine in anticancer immunity, varied among individual subtypes of tumor-infiltrated T cells." (PMID 36345336, 2022). "M1 macrophages have the positive anti-tumor activity by upregulating the production of cytokines such as IL-6 and IL-1, which activate the T helper type 1 (Th1) reaction and further produce TNF-α, ROS, RNS, and other toxic substances to kill tumors and pathogenic microorganisms." (PMID 36313280, 2022). "Notably, TNF-α released by TAMs contributes to the activation of NF-κB in tumor cells, thus preventing tumor cell death and promoting tumor cell invasion." (PMID 35736173, 2022). "However, TNF-α promotes tumorigenesis and enhances tumor progression in chronic infection by the production of ROS and reactive nitrogen species, deregulation of apoptotic pathways and induction of matrix metalloproteinases (MMPs)." (PMID 35493517, 2022). "IL1β, IL-2, IL-12, TNF-α, and IFN-γ, known as Th1 cytokines, are associated with good prognosis in many malignancies, whereas Th2 cytokines (IL-4, IL-5, and IL-10) are associated with tumor growth and metastasis." (PMID 36090972, 2022). "Finally, we evaluated the immune regulation of PCSP-AuNPs using a mouse model with H22-tumor by testing the index of immune organs, splenic lymphocyte proliferation, cytokines levels (TNF-α and IL-10), and the CD4+/CD8+ cell ratio in the peripheral blood." (PMID 35762637, 2022). "For instance, etoposide (Triptolide)-based regimen (DELX in this case) could induce tumour cell apoptosis directly and it also enhanced apoptosis through cytotoxic agents such as TNF-α." (PMID 36156598, 2022).
tumor (continued). "In addition, the expression profile of the tumor-immunoregulatory genes TNF-α, TGF-β, IL-10, and iNOS was determined in macrophages conditioned with OSCCs tumoral media previously treated with PL, in comparison with non-treated cells." (PMID 36686704, 2022). "TNF-α was initially identified as an antitumor cytokine against a wide variety of tumor types." (PMID 35268699, 2022). "TNF is able to act as an endogenous tumor promoter to bridge inflammation and carcinogenesis." (PMID 36289890, 2022). "T cells positive for either IFNγ or TNFα were defined as tumor reactive." (PMID 35017664, 2022). "TNF-α can destroy tumor cells (OSCC) due to its response to the immune system and inflammation." (PMID 36146567, 2022). "The C3A and C5A trigger inflammatory response which is crucial step in tumor onset and progression by activating leukocytes, releasing histamine, and stimulating generation of inflammatory mediators such as IL-1, IL-6, IL-1β, IFNγ, and TNF-α." (PMID 36091114, 2022). "Expression of TNFα mRNA in tumor was significantly higher than in neighboring tissues." (PMID 36555251, 2022). "TNF α is released from the tumor micro-environment, but also directly from tumor cells." (PMID 36078095, 2022). "To test if TNFα or IL-1β cytokine signaling pathways were required to produce the robust anti-tumor immune response found when 5-FU is added to ICB, we administered TNFα or IL‐1β blocking antibodies throughout the 5-FU+ICB treatment schedule in AB1-HA tumor bearing mice." (PMID 35634282, 2022). "Macrophages have a dual effect on tumor cells: on the one hand, they can increase cancer cells’ invasion potential by TNFα and NF-κB pathways; on the other hand, they can facilitate the OC dissemination of tumors in the peritoneum by combination with VEGF, proteases, and secreted growth factors." (PMID 36142615, 2022). "Notably, Rab27a upregulates response to inflammatory stimulation by enhancing exocytosis of TNF-α, whereas downregulation of Rab27a correlates with lower neutrophil-mediated tumor cytotoxicity in TME (exocytosis)." (PMID 35927755, 2022). "DCs produce TNF-α, IL-6, IL-8, and IL-12 to participate in anti-tumor immunity." (PMID 35874717, 2022). "Therefore, some therapeutic approaches are based on the induction of TNF-α expression by tumor cells." (PMID 35406442, 2022). "Similarly, through their ability to secrete inflammatory molecules such as IL-1, IL-6 and TNFα, CAFs participate in inflammation-mediated tumor progression." (PMID 35493456, 2022). "Additionally, tumor cells can secrete some inflammatory cytokines, such as tumor necrosis factor α and interleukin-β, which can result in platelet activation and the expression of a procoagulant phenotype by endothelial cells." (PMID 35677441, 2022). "Moreover, TNF signaling plays a tumor-promoting role by inducing suppressive tumor immune microenvironment and apoptosis resistance in HNSCC." (PMID 35873484, 2022). "In addition, the interaction between NK cells, effective T cells, and antitumor macrophages by secreting IFN-γ and tumor necrosis factor-alpha (TNF-α) at the tumor site increases the cytotoxic ability of NK cells." (PMID 35356739, 2022). "Inhibition of TGF-β enhanced the proinflammatory potential of TANs (N1), including cytotoxic CD8+ T lymphocyte activation, reactive oxygen species-dependent direct killing of tumor cells, and high expression of proinflammatory cytokines such as TNF-α and CCL3 and the costimulatory molecule ICAM-1." (PMID 35328639, 2022). "As a result, researchers found that Ag-coupled BPQDs promote the release of Ag+ under NIR laser irradiation and enhance the phagocytosis of Ag+ by macrophages at tumor sites, which further motivates the release of inflammatory factors such as TNF-α and IL-6 to enhance the immunogenicity of ICD." (PMID 35859703, 2022). "However, the PAR1 inhibitor reduced the rKLK6-promoted tumor growth and serum levels of TNF-α and CXCL1." (PMID 36552865, 2022).
tumor (continued). "Furthermore, TNF-α is an inflammation-related cytokine, which is related to drug resistance of tumor cells." (PMID 35477364, 2022). "Further analysis, revealed that the convertases found in cancer cells contribute to metastasis by enhancing the level of active cytokines (TNF, Il-1) involved in the first step of cancer cell and endothelial cell interaction required for liver colonization by tumor cells." (PMID 35493456, 2022). "Moreover, TNF-α has been proposed as an endogenous tumor promoter involved in human cancer development and it can trigger tumor promotion in humans." (PMID 35737058, 2022). "It has been demonstrated that MDSCs-derived exosomes contain matrix metalloproteinases (MMPs) and different cytokines, chemokines, and growth factors (CSF, VEGF, MCP, SDF1α, TNFα, and IFNγ), which establish a pro-metastatic microenvironment that allows the metastatic progression of tumor cells." (PMID 35757002, 2022). "Moreover, administration with calcitriol led to more production of IFN-γ and TNF-α in tumor-infiltrating CD8+ and γδ+ T cells." (PMID 35318258, 2022). "Higher TNF-α expression was found in tumor tissue compared to healthy urothelium, and this elevation was connected to tumor size, recurrence, and progression in grade and stage, which was exerted by the angiogenic effect of TNF-α." (PMID 36140470, 2022). "The pro-tumor mechanisms include: (a) N2 neutrophils secrete cytokines such as VEGF and TNF to promote tumor angiogenesis; (b) Neutrophils secrete matrix metalloprotein 9 (MMP-9) to degrade type IV collagen of the basement membrane, promoting the infiltration of tumor cells." (PMID 35222443, 2022). "Consequently, the local regulation of the TNF system is complex and its role in cancer is controversial, and both tumor-promoting and tumor-inhibiting actions have been detected." (PMID 35432372, 2022). "In addition to the obvious effect of phototherapy in reducing the neonatal serum bilirubin levels, this therapeutic modality promotes the serum tumor necrosis factor-α (TNF-α) level that can provoke the proliferation of some tumor cell lines." (PMID 35729528, 2022). "Furthermore, IFN-γ and TNF-α were markedly enriched in the tumor interstitial fluids (TIFs) retrieved from EO771-Bic tumors compared with those from EO771-GFP tumors." (PMID 35925680, 2022). "Indeed, the presence of endothelial cells localized in the fibrotic septa was observed in the tumor tissue of the mice that received TNFα-treated BCSC1 or BCSC2 cells." (PMID 36290384, 2022). "In addition, this CD4+ T cell subset also produces cytotoxic cytokines such as IFN-γ and TNF and therefore directly targets tumor cells." (PMID 35574343, 2022). "Adipose tissue is not only involved in energy storage, but also, as a major endocrine organ, participates in the formation of the tumor microenvironment by secreting various hormones and cytokines, such as leptin, adiponectin, and tumor necrosis factor alpha (TNF-α)." (PMID 36361525, 2022). "The pro-tumour function of neutrophils can be implicated in tumour initiation by prostaglandin E2 (PGE2) expression, the promotion of tumour growth by TNF-induced IL-17-producing CD4+ T cells and by matrix metalloproteinase 8 or 9 (MMP8-MMP9 that remodel the ECM and induce angiogenesis." (PMID 35406451, 2022). "MC-mediated anti-tumor activities relate to their ability to produce IL-1, IL-6, TNFα that induce apoptosis in tumor cells, together with chondroitin sulfate, that could exert a decoy activity by inhibiting metastases." (PMID 36338516, 2022). "Among these, the TNF signaling pathway and NF-κB signaling pathway exist in many important cellular processes, such as inflammatory response, proliferation and metastasis of tumor cells, and occurrence and development of various tumors." (PMID 36578029, 2022).